TBC1D30 (TBC1 domain family member 30)
Description:
May act as a GTPase-activating protein for Rab family protein(s).
Synonyms: KIAA0984
Tractability: Antibody: UniProt places it where antibodies can reach, with high confidence; its Gene Ontology location is reachable by antibodies, with high confidence; the Human Protein Atlas places it where antibodies can reach. PROTAC: ubiquitination databases record sites on it.
Gene: Protein-coding gene on chromosome 12 (64,759,484 to 64,881,033, forward strand). Ensembl gene ENSG00000111490.
Subcellular location: Cell membrane
Subcellular location (Human Protein Atlas): Plasma membrane; Mid piece; Principal piece
Gene Ontology:
Molecular function: GTPase activator activity; small GTPase binding
Biological process: negative regulation of cilium assembly; positive regulation of GTPase activity
Cellular component: ciliary basal body; cilium; plasma membrane
Genetic constraint (gnomAD): Loss-of-function variants: 26 observed, 55.24 expected, observed/expected ratio (o/e) 0.47, 90% interval 0.34 to 0.65. The upper end of that interval is the gene's LOEUF score, 0.65, which puts it in group 2 of 6, group 1 being the genes least tolerant of losing a copy. Missense variants: 775 observed, 943.33 expected, observed/expected ratio (o/e) 0.82, 90% interval 0.77 to 0.87. Synonymous variants: 299 observed, 363.14 expected, observed/expected ratio (o/e) 0.82, 90% interval 0.75 to 0.91.
Homologues: Orthologues: chimpanzee TBC1D30 (99% identical), macaque TBC1D30 (94% identical), mouse Tbc1d30 (91% identical), pig TBC1D30 (90% identical), rabbit TBC1D30 (87% identical), dog TBC1D30 (86% identical), rat Tbc1d30 (86% identical), guinea pig TBC1D30 (83% identical), tropical clawed frog tbc1d30 (70% identical), zebrafish tbc1d30 (58% identical). Paralogues in human: SGSM1 (15% identical), SGSM2 (14% identical), TBC1D9B (14% identical), TBC1D8B (14% identical), EVI5 (13% identical), EVI5L (13% identical), TBC1D9 (13% identical), TBC1D8 (13% identical), USP6NL (12% identical), TBC1D10B (12% identical), TBC1D2B (11% identical), TBC1D10A (11% identical), and 33 more.
Diseases named in the same sentence as TBC1D30 in open-access papers:
TBC1D30 is named in the same sentence as 4 diseases in open-access papers, as found by Europe PMC text mining. Sharing a sentence is not in itself a finding about the gene and the disease. The quoted sentences say what the papers report.
glioblastoma multiforme (1 paper, 2025). "TBC1D30 has been identified as one of the putative biomarkers for temozolomide resistance in patients with primary glioblastoma multiforme." (PMID 40662145, 2025).
tumor (3 papers, 2018 to 2021). "The β-value of TBC1D30 in sporadic IME CRC (0.36 ± 0.00) was higher than that in FAP IME neoplasms (0.21 ± 0.01), which was similar to that in sporadic LME CRC (0.16 ± 0.00)." (PMID 30220972, 2018). "We observed a higher mRNA expression of TBC1D10C, TBC1D4, TBC1D12, TBCK, TBC1D5, TBC1D30 and a lower expression of TBC1D24 in patients with tumor compared with tumor free patients." (PMID 33194704, 2020).
TBC1D30 also shares sentences with these, for which no sentence is quoted: bladder cancer (1 paper); skin cutaneous melanoma (1).